LINC02525 (long independently transcribed non-coding RNA 2525)
Synonyms: TP53LC14; lncNB1; RP1-40E16.9
Gene: Long non-coding RNA gene on chromosome 6 (3,182,626 to 3,195,784, reverse strand). Ensembl gene ENSG00000230269.
Diseases named in the same sentence as LINC02525 in open-access papers:
LINC02525 is named in the same sentence as 4 diseases in open-access papers, as found by Europe PMC text mining. Sharing a sentence is not in itself a finding about the gene and the disease.
LINC02525 shares sentences with these, for which no sentence is quoted: neuroblastoma (7 papers); tumor (4); cancer (2); skin melanoma (1).